BRAF (B-Raf proto-oncogene, serine/threonine kinase)
Diseases named in the same sentence as BRAF in open-access papers (continued):
Sharing a sentence is not in itself a finding about the gene and the disease.
melanoma (continued). "Patients with BRAF-mutated melanoma are also eligible for adjuvant immunotherapy; the optimal adjuvant therapy has not yet been established, as combination BRAF and MEK inhibition has not been directly compared with immunotherapy." (PMID 39542696, 2024). "We performed RNA-seq on EGFR-mutant PC9 NSCLC cells treated with the EGFR inhibitor gefitinib and BRAF-mutant SKMEL28 melanoma cells treated with the BRAF inhibitor dabrafenib to investigate the scope of the transcriptional changes in each system and to uncover shared mechanisms of drug tolerance." (PMID 38473364, 2024). "Notably, the expression dynamics of both HDAC10 and SPARC are influenced by the BRAF activity state in BRAF mutant melanoma cells (A375 and WM793)." (PMID 38650694, 2024). "Better understanding of off-target effects could help to identify molecular mechanisms behind AEs and guide the continued development of therapies for BRAF-mutant melanoma." (PMID 38839106, 2024). "Additionally, most melanoma is associated with upregulation of RAS signaling with other common tumor-activating mutations including neuroblastoma ras viral oncogene homolog and BRAF." (PMID 39687068, 2024). "Furthermore, identifying personalized neoantigens in melanomas with BRAF and NRAS mutations is pivotal in constructing immunogenic mRNA vaccines, paving the way for highly personalized melanoma therapy." (PMID 39582535, 2024). "which also saw lower use of BRAF/MEK inhibitors compared with ICIs, and a decline in the use of BRAF/MEK inhibitors after 2015 among a cohort of older patients diagnosed with advanced melanoma between 2012 and 2017 who received immunotherapy or targeted therapy." (PMID 39194340, 2024). "Since the current treatment choice for melanoma, including BRAF/MEK inhibitors or check blocker therapy, has drawbacks, understanding these nonapoptotic RCDs may help to identify new therapeutic targets for melanoma treatment." (PMID 38336727, 2024). "Melanomas with mutations in NRAS, the second most prevalent mutated proto-oncogene in melanoma, are characteristically more aggressive and susceptible to developing resistance to treatment when compared to BRAF mutants." (PMID 38732242, 2024). "The NeoTrio trial (ClinicalTrials.gov registration: NCT02858921) was designed to determine whether targeted therapy (dabrafenib plus trametinib) enhances the benefit of neoadjuvant anti-PD-1 (pembrolizumab) in stage III resectable BRAF-mutant melanoma." (PMID 38907159, 2024). "The NeoCombi phase II trial (NCT 01972347) evaluated the safety and efficacy of neoadjuvant dabrafenib plus trametinib in 35 BRAF-mutant resectable stage IIIB-C melanoma patients; these patients received a treatment based on 12 weeks of neoadjuvant therapy, followed by 40 weeks of adjuvant therapy." (PMID 39727691, 2024). "A previous report about the induction of BIM by MEKi led us to investigate whether BIM is upregulated in BRAF WT melanoma cells after treatment with our combination." (PMID 38263136, 2024). "With regard to anatomic location, NF1 mutant tumors (n = 22/47, 46.8%), TWT melanomas (n = 14/33, 42.4%) and co-mutant tumors (n = 7/20, 35%) occurred more frequently on the head/neck compared with BRAF or NRAS mutant tumors (n = 24/154, 15.6%; p < 0.001, chi-squared test)." (PMID 38611025, 2024). "The highest SNAI1 mRNA expression was observed in BRAF+ and BRAF− melanoma." (PMID 39273022, 2024). "About half of all melanomas present with a gain-of-function mutation in the mitogen-activated protein kinase (MAPK) / extracellular signal-regulated kinase (ERK) pathway, specifically in the kinase BRAF, promoting proliferation and survival." (PMID 39165562, 2024). "In this follow-up study, we aimed to investigate the clinical management and outcomes of patients with advanced melanoma in the metastatic/unresectable and the adjuvant setting, approximately a decade after the introduction of ICIs and BRAF/MEKi into clinical use." (PMID 38473216, 2024).
melanoma (continued). "In Asian individuals with melanoma, reduced UV signature and TMB may contribute to a lower BRAF mutation rate and a lower response rate to immunotherapy." (PMID 38469735, 2024). "Another significant mutational driver is NRAS, which is notably found in melanoma cases without BRAF mutations." (PMID 39234260, 2024). "Genetic fusions involving anaplastic lymphoma kinase (ALK), neurotrophic receptor tyrosine kinase 1 (NTRK1), ROS proto-oncogene 1 (ROS1), rearranged during transfection (RET), and B-Raf proto-oncogene serine/threonine kinase (BRAF) genes are frequently observed in this type of melanoma." (PMID 39202970, 2024). "Future research should continue to focus on optimizing existing therapies, identifying and validating new therapeutic targets, and developing more precise and personalized approaches to overcome the intrinsic and acquired resistance mechanisms characteristic of BRAF-mutant melanoma." (PMID 39336897, 2024). "BRAF wildtype melanomas were present in 54% of the patients, and 63% had elevated levels of LDH." (PMID 39061198, 2024). "Furthermore, certain mutations within BRAF and NRAS melanoma-associated genes lead to overexpression of iNOS, subsequently promoting malignant cell survival through NO release and anti-apoptotic signaling." (PMID 39519202, 2024). "In addition, they suggest the therapeutic potential of combining miR-876 overexpression with BRAF inhibition as a rational therapeutic strategy for melanoma." (PMID 39138582, 2024). "In addition, YAP confers immune evasion in BRAF inhibitor resistant melanoma cells by promoting PD-L1 expression, which can be targeted by immune checkpoint therapy." (PMID 38164167, 2024). "In cases of melanoma where neither BRAF nor RAS gene mutations are present, the MAPK pathway can still become activated through alternative autocrine mechanisms." (PMID 38534742, 2024). "Furthermore, TSLNC8 reduction prevents apoptosis in melanoma cells sensitive to BRAF inhibitors following PLX4720 therapy." (PMID 39777348, 2024). "Hence, the loss of PTEN is majorly responsible for the dysregulation of PI3K/Akt and RAS/MAPK pathways in BRAF mutant melanoma." (PMID 39238805, 2024). "Patient #27, indeed, had multiple recognized melanoma drivers including BRAF p.V600K, RAC1 p.P29S, pTERT C228T and KRAS p.G12A, this latter arising at the time of progression; thus, patient #27 represents a good example of a combined intrinsic (RAC1 mutation) and acquired (KRAS mutation) resistance." (PMID 38548846, 2024). "As for S100B, it is a valuable serum biomarker in the follow‐up of stage III and IV melanoma patients, particularly in early detection of progressive disease as well as in the prediction response to BRAF inhibitors and anti‐programmed cell death protein 1 (PD‐1) therapy." (PMID 38775220, 2024). "The National Comprehensive Cancer Network melanoma guidelines do not recommend the triplet regimen as first‐line treatment for BRAF‐mutated melanoma." (PMID 38087810, 2024). "Targeting this signalling pathway delayed tumour progression, suggesting that neural crest stem cell melanomas are resistant to BRAF/MEK inhibitors and thus, may drive tumour recurrence." (PMID 38241976, 2024). "Personalized immunotherapies for BRAF-mutant melanomas present several challenges." (PMID 39336897, 2024). "In addition to age, gender and BRAF status, the melanoma stage has an impact on the discontinuation of adjuvant treatment." (PMID 39517999, 2024). "BRAF mutation, which can be detected in 35–50% of melanomas, is a frequent oncogenic event in melanomas that develop on sun-exposed skin without pronounced solar elastosis, regardless of histological subtypes." (PMID 39272837, 2024). "As a result, nivolumab is now approved as first-line therapy for previously untreated melanoma that does not have a BRAF mutation." (PMID 39127974, 2024).
melanoma (continued). "Therefore, we conclude that MAP3K3 contributes to YAP-dependent BRAF inhibitor resistance and other malignant behaviors in melanoma cells and is a promising target for anticancer drug development." (PMID 38622197, 2024). "For instance, in BRAF mutant melanoma, in which targeted inhibitors are known to be at their highest performance, immune checkpoint inhibitors showed a 20% benefit over targeted compounds in terms of overall survival among therapy-naïve and metastatic patients." (PMID 38485987, 2024). "While vemurafenib demonstrated high efficacy against BRAF-mutated melanomas, it failed to produce high response rates in colorectal carcinomas." (PMID 38612902, 2024). "Therefore, we investigated the combination of both therapeutics to test their effects on BRAF-WT melanoma cells and compared them with monotherapy using the MEKi trametinib." (PMID 38263136, 2024). "Apoptosis in BRAF V600E melanoma cells can be mediated by upregulating BimS isoform expression." (PMID 38462618, 2024). "The BRAF V600E mutation usually occurs after non-chronic, intermittent sun exposure, and it is associated with a superficial spreading type of melanoma that has a better prognostic than other types and is more promising in terms of targeted therapies." (PMID 39063046, 2024). "Moreover, men with Class 1 BRAF mutant melanoma are less likely to benefit from BRAF + MEK inhibitor therapy." (PMID 38275886, 2024). "By tumor characteristics, ORR was 71.4% (95% CI, 29%-96%) for primary mucosal melanoma versus 24.1% (95% CI, 14%-38%) for primary cutaneous melanoma, and ORR was 31.5% (95% CI, 20%-46%) for BRAF wild-type melanoma versus 15.4% (95% CI, 2%-45%) for BRAF-mutant melanoma." (PMID 38956747, 2024). "Overall, our findings contribute to a better understanding of the molecular mechanisms underlying melanoma resistance to targeted therapies and provide insights into potential strategies to improve treatment outcomes for patients with BRAF- or NRAS-mutant melanomas." (PMID 39436655, 2024). "Since Ma-Mel-63a cells that were long-term exposed to BRAFi and MEKi (Ma-Mel-63a dr) turned out to be still sensitive to BRAF and MEK inhibition, we induced BRAFi- and MEKi resistance in the BRAFV600-mutated melanoma cell line SK-Mel-28 by long-term exposition to vemurafenib and cobimetinib." (PMID 39835134, 2024). "Using fixed melanoma tumor samples from our institution’s biobank, we set out to determine whether BRAF-targeted therapy or immunotherapy yielded better outcomes for BRAF-mutant advanced melanoma patients." (PMID 38473384, 2024). "Additionally, in advanced BRAF wild-type melanoma patients, a retrospective study comparing dual ICI with single ICI initially suggested better OS." (PMID 39582535, 2024). "In skin cancers, CAFs express different markers and in advanced melanoma, they could be involved in resistance to immunotherapy and BRAF inhibitors." (PMID 39202425, 2024). "Currently, three BRAF inhibitors (BRAFi) are clinically approved for the treatment of BRAF-V600E and BRAF-V600K mutant melanoma, namely vemurafenib, dabrafenib, and encorafenib, commonly administered together with the MEK inhibitors (MEKi) cobimentinib, trametinib, or binimetinib, respectively." (PMID 38839106, 2024). "Moreover, the combination of BRAF-targeted therapy with immunotherapy in the neoadjuvant setting for the treatment of melanoma was recently investigated (ClinicalTrials.gov identifier: NCT02858921)." (PMID 39582535, 2024). "Both patients with BRAF-WT and BRAF-mutant melanomas displayed benefit from nivolumab therapy." (PMID 39727691, 2024).
melanoma (continued). "miR-876 overexpression sensitized melanoma cells to treatment with the BRAF inhibitor vemurafenib." (PMID 39138582, 2024). "Furthermore, it has been demonstrated that Ibrutinib can reverse the resistance that some melanoma cells acquire to BRAF inhibitors." (PMID 38790974, 2024). "To assess the response to ICD inducers, including doxorubicin and Me-ALA-based photodynamic therapy (PDT), compared to the non-ICD inducer cisplatin, we used distinct melanoma cell lines with wild-type BRAF (SK-MEL-2) and BRAFV600E mutation (SK-MEL-28, A375)." (PMID 39061208, 2024). "After all, BRAF-mutant tumors confer a poorer prognosis relative to BRAF wild-type melanoma." (PMID 38539487, 2024). "Similarly, this study identified that BRAF inhibition in melanoma induces oxidative phosphorylation through upregulation of PGC1α, creating an adaptive metabolic program that limits the efficacy of BRAF‐targeted therapies." (PMID 39494561, 2024). "Approximately 50–60% of melanomas bearing mutations in the protein kinase BRAF are eligible for treatment with BRAF and MEK inhibitors, targeting mutant forms of BRAF (BRAFi) and MEK (MEKi) in the mitogen-activated protein kinase (MAPK) pathway to block cancer cell survival signals." (PMID 39409881, 2024). "Moreover, the ESMO guidelines require BRAF testing in patients with melanoma, which can lead to further genetic sequencing." (PMID 39336897, 2024). "The identification of NRAS mutations is not only essential for understanding melanoma’s genetic diversity, but also plays an important role in clinical decision-making, particularly in cases without BRAF mutations." (PMID 38474231, 2024). "We therefore hypothesized that ATOX1 is involved in the combination-induced nuclear copper accumulation in BRAF WT melanoma cells." (PMID 38263136, 2024). "In an independent experiment, encorafenib or binimetinib (MEK inhibitor) alone showed a rapid blockage of the MAPK pathway after 30 minutes in a preclinical model of melanoma, a tumor type with very good response to BRAF inhibitor single agent, as well as in BRAFV600E PMP cells." (PMID 39018564, 2024). "Notably, these trials have reported a marked improvement in recurrence‐free survival (RFS) among melanoma patients treated with high‐dose interferon‐α, immune checkpoint inhibitors (pembrolizumab, nivolumab), and BRAF/MEK inhibitors." (PMID 38212945, 2024). "In addition to its influence on BRAF-mutant melanoma, binimetinib has synergistic antitumor clinical activity in tumors like melanoma harboring neuroblastoma-rat sarcoma (NRAS) mutations and Kirsten Rat Sarcoma viral oncogene (KRASm) NSCLCs." (PMID 39090580, 2024). "From 2012, BRAF inhibitors became available for patients with BRAF-mutant melanoma." (PMID 38370537, 2024). "Thus, the BRAF inhibitor vemurafenib is a commonly used targeted therapy and improves melanoma survival rates." (PMID 38893071, 2024). "The introduction of drugs that directly target BRAF-mutant protein (BRAF inhibitors) and of agents that stimulate immune response through targeting of immune check inhibitor consistently improved the survival of melanoma BRAFV600-mutant patients with unresectable/metastatic disease." (PMID 39727691, 2024). "The CDKN2A gene remains understudied in melanoma compared to BRAF alterations." (PMID 38792946, 2024). "Therefore, we combined trametinib, the first FDA-approved MEK inhibitor for the treatment of BRAF V600E-mutant melanoma, to treat tumors with acquired resistance to osimertinib." (PMID 39528952, 2024). "Compared with patients without a BRAF mutation, BRAF-mutated melanomas are seen in the younger age group of <40 years old and in anatomical regions with zero-to-low cumulative sun damage (CSD)." (PMID 38247727, 2024). "Such strategies may synergize with existing immunotherapies, including immune checkpoint inhibitors, to improve response rates and overall survival in patients with BRAF-mutant melanoma." (PMID 39336897, 2024).
melanoma (continued). "Similarly, somatic mutations leading to MAPK pathway activation have been identified as the basis for over 90% of malignant melanoma (MM), notably BRAF and NRAS." (PMID 39355740, 2024). "Given that i) miR-579-3p is a negative regulator of BRAF-V600-MAPK signaling and ii) miR-579-3p expression is under the transcriptional control of MITF, we decided to measure MITF protein levels following MAPK signaling pathway inhibition in BRAF-mutant melanoma cells." (PMID 38472212, 2024). "The introduction of BRAF inhibitors marked a significant advancement in the management of advanced melanoma, highlighting the critical role of the BRAF and MEK proteins in melanoma pathogenesis through their involvement in the mitogen-activated protein kinase (MAPK) pathway." (PMID 39229331, 2024). "Finally, in a retrospective two-center study of 56 patients with metastatic BRAF wild-type melanoma who underwent initial FDG-PET/CT prior to ICI, the primary objective was to predict prognosis based on radiomic parameters." (PMID 38970050, 2024). "Another retrospective analysis suggested that the circulating oncogenes miR-579-3p and oncomiR miR-4488 could be used to predict whether targeted therapies are appropriate for patients with BRAF-mutant melanoma." (PMID 39659781, 2024). "To verify whether trametinib plus CuET affects the survival of BRAF WT melanoma cells in a more physiological three-dimensional (3D) environment, we evaluated the cellular viability of melanoma spheroids in a short-term viability assay." (PMID 38263136, 2024). "In BRAF+ melanoma, however, strong diffuse cytoplasmic staining was noticed." (PMID 39273022, 2024). "Moreover, the Cancer Osaka thyroid (COT) kinase has been reported to be overexpressed in drug-resistant melanomas and to induce resistance to BRAF inhibition through the direct activation of the MEK/ERK signaling pathway." (PMID 39199632, 2024). "Currently, BRAF V600 mutational testing is only available for the primary metastasis of a malignant melanoma, and any other metastasis that arises later will not be tested." (PMID 38127894, 2024). "For example, BRAF mutation alone is not sufficient for inducing melanoma as BRAF mutations are frequently observed in benign nevi." (PMID 37239381, 2023). "Notably, these metabolic alterations have been proposed as a lineage program in melanoma cells resistant to BRAF/MEK inhibition." (PMID 37834284, 2023). "With either immunotherapy, or targeted treatment, Varaljai and colleagues observed that a decrease in BRAF V600E ctDNA levels preceded radiologic detection of response in 80% of melanoma responders with an average lead-time window of 1.5 months (range, 0.023 to 3.45 months; p = 0.003)." (PMID 38201222, 2023). "In addition to primary cytotoxicity, LNPs have been evaluated as a therapeutic strategy to combat drug resistance, specifically, among BRAF-mutant melanoma cell lines." (PMID 37622997, 2023). "As patients with BRAF mutant melanoma have both ICI and TT as their first-line treatment options, the question whether the sequence matters was addressed." (PMID 37543586, 2023). "Since ABL1/2 play important roles in driving melanoma progression and are activated by ERK pathway components (BRAF, ERK) in BRAF-mutant melanomas, we examined whether their activities are elevated during MEKi resistance in NRAS-driven melanomas." (PMID 36765910, 2023). "In literature three histology-independent “basket” researches were reported, exploring the efficacy of Vemurafenib in BRAF V600E mutant non-melanoma cancers, in which 2 SS (among 6 STS patients) with BRAF V600E mutation enrolled, and one report of 2 patients with SS expressing BRAF V600E mutation." (PMID 37417899, 2023). "Indeed, treatment-naïve melanoma cells plated on ECM autonomously produced and assembled by dedifferentiated resistant or TT-exposed melanoma cells are protected from the anti-proliferative effect elicited by oncogenic BRAF inhibition." (PMID 36774337, 2023).